YTHDF3 (YTH N6-methyladenosine RNA binding protein F3)
Diseases named in the same sentence as YTHDF3 in open-access papers (continued):
Sharing a sentence is not in itself a finding about the gene and the disease.
breast cancer (continued). "Nonetheless, it is important to acknowledge that YTHDF3 may regulate the expression of multiple genes in breast cancer, and its effects on breast cancer may be attributed to its broad impact on various targets." (PMID 39372951, 2024). "Moreover, the YTHDF3-m6A-FGF2 model suggests the potential for a new therapeutic strategy in breast cancer treatment through the suppression of YTHDF3 expression." (PMID 39372951, 2024). "Furthermore, our research reveals the pronounced promotion of malignant processes, including proliferation, migration, and invasion, by YTHDF3 in breast cancer cells." (PMID 39372951, 2024). "Moreover, YTHDF3 was frequently amplified (6%) and contributed to the high expression levels of YTHDF3 in human breast cancer." (PMID 36606187, 2022). "YTHDF1 and YTHDF3 were also found to overexpress in breast cancer." (PMID 35721510, 2022). "Interestingly, YTHDF3 was also found to play the key role in colorectal cancer and breast cancer brain metastasis." (PMID 36471428, 2022). "Similarly, YTHDF3 significantly promotes the binding of eIF3a to m6A residues within the 5′ UTR of YTHDF3 mRNA to enhance cap-independent translation in breast cancer brain metastases." (PMID 35093087, 2022). "Interestingly, in a separate study, miR-106b-5p gene transfection downregulated the expression of YTHDF3, which enhanced cell proliferation, migration and invasion of oestrogen-induced breast cancer." (PMID 34044876, 2021). "As a m6A reader, YTHDF3 was overexpressed and clinically correlated with breast cancer brain metastases (BCBM), suggesting that YTHDF3 overexpression was indispensable for multiple steps of BCBM through facilitating ST6GALNAC5, GJA1, EGFR, and VEGFA expressions." (PMID 34952600, 2021). "High expressions of YTHDF1 and YTHDF3 were related to poor survival of patients with breast cancer." (PMID 34804948, 2021). "Furthermore, the deceased patients had relatively reduced expression of FTO, METTL3, and METTL14 in tumor tissues, and increased levels of YTHDF1 and YTHDF3 than the alive patients who were diagnosed with breast cancer at the same period." (PMID 34804948, 2021). "In addition, YTHDF1, YTHDF2 and YTHDF3 are highly expressed in breast cancer and enhance cell proliferation, migration and invasion." (PMID 34044876, 2021). "Especially, YTHDF3 is an independent prognostic factor of OS in breast cancer patients." (PMID 33292526, 2020). "In addition, YTHDF3 can be used as a helpful biomarker in various cancers, including breast cancer." (PMID 42036761, 2026). "Moreover, miR-106b-5p was found to downregulate YTHDF3 expression in breast cancer." (PMID 39440064, 2024). "Additionally, in several intrinsic molecular subtypes of breast cancer, heightened expression of YTHDF3 is accompanied by increased patient mortality rates, suggesting its importance as an oncogene in breast cancer and its selection during the cancer evolution process." (PMID 39372951, 2024). "In addition, we observed that YTHDF3 mRNA levels was upregulated in breast cancer." (PMID 36606187, 2022). "Therefore, YTHDF3 may be considered a promising biomarker for predicting breast cancer patient survival." (PMID 36606187, 2022). "Accumulating evidence has indicated that YTHDF3 promotes tumor progression including breast cancers, small-cell lung cancer (SCLC), CRC, and other types; however, the role of YTHDF3 in TNBC is not well understood." (PMID 40406242, 2025). "Successful knockdown of YTHDF3 was achieved in MCF-7 and MDA-MB-231 breast cancer cells using siRNAs (siY3-1 and siY3-2)." (PMID 39372951, 2024). "To investigate this, we performed RIP experiments in breast cancer cell lines, which revealed an interaction between FGF2 and YTHDF3 mRNA." (PMID 39372951, 2024). "YTHDF3 regulates the translation of FGF2 in an m6A-dependent manner, influencing the malignant progression of breast cancer cells." (PMID 39372951, 2024).
breast cancer (continued). "Many m6A readers have been proven to be associated with distant metastasis of breast cancer and are considered promising prognostic biomarkers and therapeutic targets for breast cancer, here IGF2BP1 and YTHDF3 are examples." (PMID 39342406, 2024). "YTHDF1/eEF1-mediated translational elongation of KRT7 mRNA and YTHDF3-induced mRNAs translation of ST6GALNAC5, GJA1, and EGFR is involved in breast cancer lung and brain metastasis, respectively." (PMID 36999016, 2023). "For example, m6A modification mediated by the cooperation of METTL14, ALKBH5, and YTHDF3 was reported to influence the cell cycle, induce the progression of EMT, and contribute to angiogenesis of cancer cells in breast cancer." (PMID 34996459, 2022). "In breast cancer, the overexpression of YTHDF1, YTHDF3, and KIAA1429 predicted a poor prognosis in terms of OS." (PMID 35806168, 2022). "These breast cancer patients with distinct molecular subtypes all represented lower expression of FTO, METTL3, and METTL14, and higher expression of YTHDF1 and YTHDF3 in tumor compared to the corresponding adjacent samples." (PMID 34804948, 2021). "It has been reported that the m6A reader YTHDF3 promotes ribosome loading with YTHDF1, and a high YTHDF3 expression in breast cancer clinically correlates with brain metastases." (PMID 34976022, 2021). "In GSE70905, YTHDC1 (p < 0.05), IGFBP1 (p < 0.001), ALKBH5 (p < 0.001), WTAP (p < 0.001), YTHDF3 (p < 0.001) and HNRNPA2B1 (p < 0.001) were down-regulated in breast cancer to the adjacent." (PMID 33362863, 2020). "According to the clinical database of breast cancer of TCGA, RBM15B, YTHDF3, ZC3H13, METTL16, and LRPPRC were picked up indicating strong associations with clinical characteristics." (PMID 33362863, 2020). "In HER-2 (+) breast cancer patients, METTL16 expressed lower than the HER-2 (−), but YTHDF3 expressed higher than the HER-2 (−)." (PMID 33362863, 2020). "From another perspective, Kaplan-Meier Plotter platform showed that the relatively high expression of YTHDF3 and LRPPRC and the relatively low expression of RBM15B, ZC3H13, and METTL16 in breast cancer patients had worse Relapse-Free Survival (RFS)." (PMID 33362863, 2020). "The high expression of YTHDF3, ZC3H13, LRPPRC, and METTL16 indicated poor survival rate in patients with breast cancer, while high expression of RBM15B pointed to a better survival rate." (PMID 33362863, 2020). "Mechanistically, YTHDF3 enhances the expression of HIF1α and LDHA and glycolysis by inducing the phosphorylation of mTOR, and finally promotes the occurrence and development of breast cancer." (PMID 42036761, 2026). "Moreover, depletion of FGF2 markedly suppressed the biological functions of breast cancer cells, while reducing FGF2 expression in YTHDF3-overexpressing breast cancer cell lines substantially alleviated the malignant progression." (PMID 39372951, 2024). "In addition, all breast cancer cell lines, except the HER2+ cell line SK-BR-3, exhibited increased levels of YTHDF3 expression compared to the normal mammary epithelial cell line MCF-10A." (PMID 39372951, 2024). "YTHDF3 controls FGF2 translation in an m6A-dependent manner, directly targeting FGF2 by affecting the stability of FGF2 protein, thus influencing the malignant progression of breast cancer cells." (PMID 39497721, 2024). "Combined with our correlation analysis, YTHDF3 may upregulate the expression of SLC31A1 by increasing its m6A methylation, promoting the metastasis of breast cancer cells." (PMID 37275369, 2023). "YTHDF3 is another organ-specific metastasis driver that regulates the translation of key metastasis genes such as T6GALNAC5, GJA1, EGFR, and VEGFA to promote breast cancer brain metastasis." (PMID 38102722, 2023).
breast cancer (continued). "In breast cancer, YTHDF1 and YTHDF3 are frequently amplified and consequently overexpressed, and significant correlations with intrinsic subclasses and nodal metastasis have been described, suggesting their use for prognosis stratification and therapeutic intervention in breast cancer." (PMID 37369946, 2023). "Overexpression of the m6A reader YTHDF3 or the m6A demethylase ALKBH5 may enhance the transcription of m6A-enriched genes in breast cancer, facilitating breast cancer brain metastasis." (PMID 34976022, 2021). "YTHDF3 has been verified to correlate with several kinds of carcinoma, such as colorectal cancer (CRC), gastric cancer, bladder cancer, breast cancer, and so on." (PMID 33362863, 2020). "In addition, breast cancer patients with changes in YTHDF3 expression have worse OS rates compared with those with no YTHDF3 change 33, which is consistent with our findings." (PMID 36606187, 2022). "YTHDF3 promoted translation of CTNNB1, contributing to proliferation, migration, and maintenance of cancer stem–like properties in ocular melanoma, and mediated breast cancer brain metastasis through increasing m6A-dependent ST6GALNAC5 and epidermal growth factor receptor expressions." (PMID 36183833, 2022). "As expected, silencing YTHDF3 with shRNAs in MCF-7 and MDA-MB-231 breast cancer cells reduced in FGF2 protein levels without affecting its RNA levels." (PMID 39372951, 2024).
colorectal cancer (32 papers, 2019 to 2026). A primary or metastatic malignant neoplasm that affects the colon or rectum. "In colorectal cancer, circYAP encodes the YAP-220aa micro-protein in a translation program that requires YTHDF3 and eIF4G2 and that supports invasion and liver metastasis, providing a metastasis-proximal example of m6A-dependent circRNA translation." (PMID 41301491, 2025). "GAS5 has been reported to interact with and trigger YAP phosphorylation and degradation to inhibit the progression of colorectal cancer, and to be negatively regulated by the mA reader YTHDF3." (PMID 37355516, 2023). "Previous studies showed that the stability of lncRNA GAS5 was destroyed by YTHDF3 and consequently promoted progression of colorectal cancer." (PMID 35183226, 2022). "Mechanistically, YTHDF3 can bind m6A-modified lncGAS5, and promote the decay of lncGAS5, which can inhibit colorectal cancer progression by inhibiting YAP." (PMID 34733885, 2021). "For instance, YTHDF3, an m6A reader, is considered to be a worse prognosis factor and can promote cancer progression in colorectal cancer." (PMID 34733885, 2021). "lncRNA GAS5 negatively regulated by YTHDF3 (reader) was demonstrated to be a tumor-suppressor in colorectal cancer." (PMID 34238292, 2021). "By negative feedback, m6A-modification of GAS5 accelerates the metastasis of colorectal cancer through the degradation of GAS5 transcripts that bind to the YTHDF3 protein." (PMID 33050646, 2020). "In addition, YTHDF3 affects the occurrence and progression of colorectal cancer through the regulation of m6A modification." (PMID 39372951, 2024). "Negatively controlled by YTHDF3, the lncRNA GAS5 could restrain colorectal cancer progression by causing YAP (Yes1 associated transcriptional regulator) phosphorylation and degradation." (PMID 32793593, 2020). "Therefore, YTHDF3 also plays the role of an oncogene in colorectal cancer." (PMID 36324258, 2022). "Moreover, a recent study showed that YTHDF3 knockdown could trigger the differential expression of 1174 protein-coding genes in colorectal cancer cells." (PMID 34709120, 2022). "For instance, YTHDF3 serves as an m6A reader to negatively regulate GAS5, thus triggering YAP phosphorylation and degradation and inhibiting the progression of colorectal cancer." (PMID 38229597, 2024). "YTHDF3, another m6A binding protein, also interacts with different LncRNAs in NSCLC, colorectal cancer and prostatic cancer." (PMID 37365581, 2023). "In colorectal cancer cells, it binds YAP and YTH N6-Methyladenosine RNA Binding Protein 3 (YTHDF3) to inhibit cancer progression." (PMID 36770654, 2023). "They found the upregulation of more m6A‐associated genes in tumour tissues than in normal tissues, as well as the downregulation of ALKBH5, YTHDF3 and METTL14 in colorectal cancer (CRC)." (PMID 34647424, 2022). "M6A reader YTHDF3 negatively regulates the long non-coding RNA GAS5, inhibiting the progression of colorectal cancer by interacting with and triggering YAP phosphorylation and degradation." (PMID 35187083, 2022). "For instance, YTHDF3 recognizes and binds to m6A-modified lncRNA GAS5 and promotes its degradation, which elevates YAP expression and promotes colorectal cancer (CRC) progression." (PMID 34646770, 2021). "But, in colorectal cancer, lower levels of GAS5 triggers the transcription of YTHDF3 by increasing the amount of nuclear YAP proteins." (PMID 33050646, 2020). "YTHDF3, an m6A reader, recognizes m6A-modified GAS5 and accelerates its decay in colorectal cancer." (PMID 41301491, 2025). "In clinical observations, the expression of lncRNA GAS5 showed a negative correlation with the protein levels of YAP and YTHDF3 in the tumors of colorectal cancer patients." (PMID 39830506, 2024). "YTHDF3 also has been indicated to bind to m6A-modified LncRNA GAS5 and facilitate LncRNA GAS5 degradation in a methylation-dependent manner, indicating a new insight into LncRNA GAS5 in colorectal cancer progression." (PMID 37365581, 2023).
colorectal cancer (continued). "Another member of the YTHDF family, YTHDF3, affects colorectal cancer progression by regulating the negative feedback axis of the lncRNA GAS5-YAP-YTHDF3 in the Hippo pathway." (PMID 35614935, 2022). "YTHDF3 inhibits colorectal cancer progression by negatively modulating the lncRNA GAS5 to generate a GAS5-YAP-YTHDF3 negative feedback loop." (PMID 34721523, 2021). "YTHDF3 was a novel target of YAP, which could facilitate the degradation of m6A modified lncRNA GAS5, thus uncovering a negative functional loop of lncRNA GAS5-YAP-YTHDF3 axis, and identifying a novel mechanism for m6A induced decay of GAS5 on YAP signaling in the progression of colorectal cancer." (PMID 34345203, 2021). "Notably, the functional link between lncRNA GAS5 and m6A modification in colorectal cancer has already been proven, where the lncRNA GAS5, YAP signaling, and YTHDF3 formed a negative feedback loop that promoted cancer progression." (PMID 35778697, 2022).
glioma (15 papers, 2020 to 2024). A benign or malignant brain and spinal cord tumor that arises from glial cells (astrocytes, oligodendrocytes, ependymal cells). "The results showed that METTL14, FTO, YTHDF1, and YTHDF3 demonstrated significant upregulation in low-grade gliomas compared to normal tissues." (PMID 38398118, 2024). "In the intricate network of glioma pathogenesis, the YTHDF family, consisting of YTHDF1, YTHDF2, and YTHDF3, and YTHDC1 and YTHDC2, as members of the YTH domain-containing family, play significant roles in the prognosis and molecular mechanisms underlying glioma." (PMID 38474421, 2024). "Among the proteins with YTH domains, YTHDF1, YTHDF2, and YTHDF3 play pivotal roles in gliomas." (PMID 37964279, 2023). "Interestingly, after searching the literature and GEPIA databases, it was found that eIF4G2 and YTHDF3 were upregulated in glioma compared with normal brain tissues (GEPIA2 screening condition: log2foldchange cutoff=1, p-value cutoff=0.01)." (PMID 33323543, 2020). "In glioma research, a bioinformatics analysis in the CGGA microarray and RNA sequencing databases showed that the levels of YTHDC2, YTHDF1, YTHDF2, and YTHDF3 were elevated in gliomas." (PMID 34721530, 2021). "Except for the genes of FHL2 and YTHDF3, there were significant differential expression of the other genes between WHO grade II and WHO grade III glioma." (PMID 33264518, 2021).
pancreatic cancer (12 papers, 2021 to 2025). "The effect of YTHDF3 on DICER1-AS1 was found to be significantly enhanced in glucose-deficient pancreatic cancer cells." (PMID 39440064, 2024). "This highlights the therapeutic potential of targeting the YTHDF3‐MYC signaling axis in pancreatic cancer." (PMID 39778021, 2025). "This posttranslational modification is regulated by ZDHHC20 and maintains the protein stability of YTHDF3, which is essential in the development of pancreatic cancer." (PMID 38821916, 2024). "Taken together, our results reveal that m6A modifications in the MYC CRD are required for YTHDF3-mediated stabilization of MYC mRNA in pancreatic cancer." (PMID 38821916, 2024). "Taken together, our data indicate that ZDHHC20-mediated palmitoylation of YTHDF3 on Cys474 promotes pancreatic cancer progression." (PMID 38821916, 2024). "Here, the authors report that ZDHHC20-mediated S-Palmitoylation of the m6A reader YTHDF3 stabilizes MYC mRNA to promote the progression of KRAS-mutant pancreatic cancer." (PMID 38821916, 2024). "To this end, we performed a clone formation assay of PANC-1 and AsPC-1 cells expressing YTHDF3 WT and the C474S mutant and found decreased proliferation of pancreatic cancer cells expressing the C474S mutant." (PMID 38821916, 2024). "In pancreatic cancer, YTHDF3 increased expression correlates with poor overall survival, and YTHDF3 regulates the lncRNA DICER1-AS1 that promotes glycolysis through inhibition of miR-5586-5p." (PMID 37369946, 2023). "Specifically, Bcl-2, Claspin, METTL3 and YTHDF3 were identified as the potential targets of celastrol treatment in pancreatic cancer cells." (PMID 38110764, 2023). "Meanwhile, analysis of TCGA database showed that YTHDF3 was significantly increased in pancreatic cancer tissues, as well as negatively correlated with DICER1-AS1 expression and overall survival." (PMID 35183226, 2022). "Furthermore, to fully understand the biological role of ZDHHC20 and YTHDF3 in pancreatic cancer, future studies using pancreas-specific deficiency of ZDHHC20 or YTHDF3 KPC mice model are warranted." (PMID 38821916, 2024). "To determine whether YTHDF3 is palmitoylated, we detected palmitoylation of endogenous YTHDF3 in pancreatic cancer cells by click chemistry and acyl-biotin exchange (ABE)." (PMID 38821916, 2024). "Notably, we found that YTHDF3 protein levels were downregulated in ZDHHC20-KO pancreatic cancer cells, and the knockdown of HSC70 or LAMP2A reversed the effects of ZDHHC20 deficiency on YTHDF3 protein levels in ZDHHC20-KO cells." (PMID 38821916, 2024). "In addition, palmitoylation is a dynamic and reversible modification, and the balance between palmitoylation and depalmitoylation of YTHDF3 in pancreatic cancer needs further exploration." (PMID 38821916, 2024). "Similarly, in vivo fluorescence imaging also showed suppression of pancreatic tumor growth in mice implanted with cells expressing the YTHDF3-C474S mutant." (PMID 38821916, 2024). "In summary, the findings present here provided in vitro and in vivo evidences demonstrating that downregulation of Bcl-2, Claspin, METTL3 and YTHDF3 was involved in celastrol-induced cellular proliferation inhibition, cell cycle arrest and apoptosis in pancreatic cancer cells." (PMID 38110764, 2023). "In this study, we showed downregulation of YTHDF3 in celastrol-treated pancreatic cancer cells." (PMID 38110764, 2023). "Collectively, our findings indicated that Claspin, Bcl-2, METTL3, and YTHDF3 might be the potential targets of celastrol treatment in pancreatic cancer cells." (PMID 38110764, 2023). "Collectively, our data clearly indicated that Claspin and Bcl-2 might be the targets of YTHDF3, and celastrol treatment downregulated Claspin and Bcl-2 in an m6A-YTHDF3-mediated manner in pancreatic cancer cells." (PMID 38110764, 2023). "Therefore, we further explored whether ZDHHC20 promotes pancreatic cancer progression via YTHDF3." (PMID 38821916, 2024).